SP1 (Sp1 transcription factor)
Diseases named in the same sentence as SP1 in open-access papers (continued):
Sharing a sentence is not in itself a finding about the gene and the disease.
colorectal cancer (continued). "Treatment with HDAC inhibitor has been previously found to decrease EGFR mRNA and promoter activity by dissociation of transcription factor SP1 from the EGFR promoter around the transcription start site of EGFR gene in colorectal cancer cells." (PMID 24707474, 2014). "On the other hand, SP1 also correlates to colorectal cancer." (PMID 35712724, 2022). "Ets1 and Sp1 regulate cell progression in colorectal cancer." (PMID 36305724, 2022). "MitA, the selective inhibitor of SP1, is reported to inhibit colorectal cancer." (PMID 35712724, 2022). "Moreover, PTPN6 also facilitates chemosensitivity of colorectal cancer cells by inhibiting specificity protein 1 (SP1)/MAPK signaling pathway." (PMID 35957898, 2022). "Additionally, SP1 was directly targeted by miR-382, a tumor suppressor gene, impeding colorectal cancer cell development and metastasis." (PMID 34257529, 2021). "miR-375 reverses chemoresistance by targeting YAP1 and SP1 in colorectal cancer." (PMID 32457613, 2020). "(a) Detection of SP1 protein levels in colorectal cancer and normal tissues by IHC." (PMID 30266084, 2018). "In addition, we found SNHG1 expression was positively correlated with SP1 expression in colorectal cancer sequencing data from TCGA, and the positive correlation was also observed in our samples." (PMID 30266084, 2018). "Our present results implicate the newly indentified miR-22/Sp1/PTEN/AKT axis might represent a potential therapeutic target for colorectal cancer." (PMID 28422727, 2017). "Thus, plasma treatment inhibited cell viability and colony formation by suppressing Sp1, which induced apoptosis and cell-cycle arrest in these two human colorectal cancer cell lines." (PMID 28225083, 2017). "Furthermore, Sp1 and Elk-1 bind to the caspase-8 promoter and induce apoptosis in colorectal cancer cells in response to SPARC treatment." (PMID 25693514, 2015). "Up-regulation of Sp1 expression has been also observed in thyroid and colorectal cancer." (PMID 23326307, 2013). "Furthermore, NCTD downregulated MMP-9 promoter activity through the inhibition of Sp-1 transactivation in colorectal cancer cells." (PMID 22615870, 2012). "Ets1, Sp1 and Src all regulate cell progression in colorectal cancer, and additionally, both Ets1 and Src are highly expressed in colorectal cancer, implying that there may be reciprocal links between Ets1, Sp1 and Src in the development of colorectal cancer." (PMID 36305724, 2022). "Interestingly, silencing of RAGE in colorectal cancer cells resulted in decreasing of Sp1 expression, which suggested that RAGE signaling may regulate Sp1 expression." (PMID 29262634, 2017). "Herein, we observed that the transcription factor SP1 physically interacts with and stabilizes the YAP/TEAD complex at regulatory genomic loci in colorectal cancer (CRC)." (PMID 39875519, 2025). "In colorectal cancer, KIF18B has been observed to interact with SP1, resulting in the upregulation of PARPBP and the maintenance of oxaliplatin resistance in oxaliplatin-resistant colorectal cancer (OR-CRC) cells." (PMID 40110038, 2025). "Finally, studies of prostate and colorectal cancers have demonstrated that miR-375 may participate in chemoresistance through interactions with Yes-associated protein 1 (YAP1) and Specificity Protein 1 (SP1) transcription factors." (PMID 36674758, 2023). "SP1 upregulated lncRNA TUG1 and promoted the tumorigenesis of colorectal cancer cells by TUG1/miR-421/lysine demethylase 2A (KDM2A)/ERK axis." (PMID 37686205, 2023). "In colorectal cancer cells, by targeting YAP1 and SP1, miR-375-3p was found to repress tumorigenesis and partially modulate the chemoresistance of 5-fluorouracil." (PMID 35205628, 2022). "Moreover, SP1 could combine with the promoter of ZFAS1 to regulate ZFAS1 in colorectal cancer." (PMID 34268302, 2021). "(c) The relation between SP1 and SNHG1 expression analyzed in colorectal cancer samples from TCGA cohort (n = 478, r = 0.202, P < 0.001)." (PMID 30266084, 2018).
colorectal cancer (continued). "In colorectal cancer Caco-2 cells, the activity of the ELMO3 promoter can be regulated by caudal-related homeobox transcription factor 2 (CDX2), which interacts with SP1." (PMID 30345300, 2018). "In colorectal cancer, SIOMICS predicted five shared motifs, which were similar to the motif of the TFs SP1, the CAC-binding protein, TFAP2A (AP-2), KLF6 (GBF), and EGR1 (KROX), respectively (the names in parentheses are the corresponding TRANSFAC TF names)." (PMID 28684851, 2017). "COE displays anti-cancer properties by inducing apoptosis via the downregulation of Sp1 in HSC-2 human oral cancer cells and cell cycle arrest in HT29 human colorectal cancer cells." (PMID 27435599, 2016). "Previous studies have shown that the transcription factors NF-κB, Sp1 and C/EBP-β can be activated through the MAPK pathways in colorectal cancer cells." (PMID 23098564, 2012). "Our results suggest that Sp1 plays a role in H2O2-induced PUMA expression and apoptosis in colorectal cancer cells." (PMID 18811981, 2008). "Abnormally elevated expression and DNA binding of Sp1, as for many of the Sp/KLF family members to which belong Sp1, has been recognized as a valuable prognostic marker in both gastric and colorectal cancers." (PMID 17961220, 2007). "Consistent to the previous study in colorectal cancer, TEAD1 could promote SP1 transcriptional activation and expression in LUAD cells." (PMID 35485206, 2022). "In humans and rats, SP1, SMADs, and hypoxia-inducible factor-1 activate transcription via direct binding to the promoter region of NT5E, whereas peroxisome proliferator-activated receptor gamma (PPAR-γ) suppresses its transcription in human colorectal cancer." (PMID 32604872, 2020). "In colorectal cancer, we found that the cofactors of TFAP2A were PPARG and SP1." (PMID 28684851, 2017). "In addition, in response to secreted protein, acidic and rich in cysteine (SPARC) expression, Sp1 and Elk-1 bind to the caspase-8 promoter and induce apoptosis in MIP101 colorectal cancer cells." (PMID 25693514, 2015). "Inhibition of Sp-1 and promotion of E-cad expression may be an effective strategy for successful treatment of CUR to resistance of CRC metastasis, and CUR is thought to be a potential chemopreventive and therapeutic drug especially in colorectal cancer." (PMID 23970932, 2013). "Therefore, we speculate that the combination of MitA or other SP1 inhibitors and CPT-11 might achieve a startling effect of reducing the side effect and enhancing the anticancer efficacy simultaneously in the treatment of colorectal cancer." (PMID 35712724, 2022).
ovarian carcinoma (71 papers, 2006 to 2026). A malignant neoplasm originating from the surface ovarian epithelium. "This partially selective inhibition of promoters controlled by Sp1, thought to be relevant for ovarian cancer, is associated with a number of antineoplastic effects, including increased apoptosis, decreased angiogenesis, and inhibition of cell growth." (PMID 33445667, 2021). "Long non-coding RNA ZFAS1 was demonstrated to be overexpressed in epithelial ovarian cancer and was associated with platinum and taxol chemoresistance via targeting a MiR-150-5p/SP1 axis." (PMID 33445667, 2021). "Sp1 was also shown to suppress microRNA 335, for which low expression has been associated with poor prognosis in ovarian cancer and enhanced ovarian cancer cell migration in vivo." (PMID 33445667, 2021). "Due to the central role of Sp1 in cell cycle regulation and cell growth, aberrations in its expression, specifically upregulation, have been linked to tumorigenesis in a number of malignancies, including ovarian cancer." (PMID 33445667, 2021). "Specific chemical inhibitors against four molecules linked with EMT—that is, Smad 2/3, ILK, AP-1, and SP-1—were added to ovarian cancer cells prior to their exposure to the malignant ascites to identify the signaling pathway(s) responsible for the induction of this process." (PMID 30609691, 2019). "Similarly, the oncoprotein HBXIP promotes the migration of ovarian cancer cells through the upregulation of S-phase kinase-associated protein 2 by Sp1." (PMID 28388957, 2017). "As expected, overexpression of Sp1 in ovarian cancer cell lines resulted in a significant increase in c-Myc protein levels." (PMID 41584043, 2026). "In contrast, Sp1 decreases miR-335 expression in ovarian cancer cells, and this is one of the rare reported examples of Sp1 as a transcriptional receptor." (PMID 36982239, 2023). "For instance, in ovarian cancer, SP1 promotes LncRNA‐DANCR‐induced tumor cell proliferation through a direct transcriptional activation." (PMID 35924788, 2022). "Hepatitis B X-interacting protein (HBXIP), an oncoprotein overexpressed in ovarian cancer, was shown to promote cell migration via induced Sp1-mediated transcription." (PMID 33445667, 2021). "A recent study suggested that SP1 promotes migration of ovarian cancer cells via direct transcriptional repression of miR-335 or inducing hypermethylation of the miR-335 promoter." (PMID 33731131, 2021). "In ovarian cancer cells, Sp1 can be upregulated, activating numerous oncogenes and leading to increased cell migration, angiogenesis, and decreased apoptosis." (PMID 33445667, 2021). "Mithramycin analogs demonstrated inhibition of Sp1 dependent transcription in cell culture lines and in human ovarian cancer xenografts." (PMID 33445667, 2021). "The promoter of the survivin gene has a typical CpG island and many SP1-binding sites, making it possible for SP1 to activate and upregulate survivin transcription, which can be found in various studies such as ovarian cancer." (PMID 34970121, 2021). "CD147, an immunoglobin that is overexpressed in ovarian cancer and noted to be an independent prognostic factor, phosphorylates Sp1, and forms a positive feedback loop in vitro." (PMID 33445667, 2021). "In an analysis of the National Center for Biotechnology Information Gene Expression DatabaseGEO database, Sp1 was found to be overexpressed in platinum-resistant ovarian cancer patients." (PMID 33445667, 2021). "LncRNA ZFAS1 is overexpressed in epithelial ovarian cancer cells and directly targets miR-150-5p to enhance the expression of specificity protein 1 (SP1), which makes ovarian cancer cells resist to cisplatin and paclitaxel." (PMID 34660304, 2021). "Sp1 is reported to bind to the claudin-3 promoter region at −112 to −74 bp in ovarian cancer cells, which is consistent with our result of −147 to 52 bp." (PMID 34831451, 2021).
ovarian carcinoma (continued). "MiR-141/KLF12/Sp1/survivin signaling pathway enhanced AR in ovarian cancer, and a transcriptomic study addressed the importance of CDKN1A-regulated quiescence for cells to survive from anoikis in head and neck squamous carcinoma." (PMID 34456997, 2021). "In ovarian cancer studies, SP1 has been found to regulate genes overexpressed in the cancer process, and the direct targeting of it by miR-128 and miR-377 can retard the proliferation of cancer cells." (PMID 34970121, 2021). "In ovarian cancer, miRNA-141 enhances the anoikis resistance of metastatic ovarian carcinoma cell by regulating Kruppel Like Factor 12/Sp1 Transcription Factor (KLF12/Sp1) axis." (PMID 32782028, 2020). "Our study provides the molecular basis for the inhibition of the SP1-12LOX axis as a potential therapeutic approach to improve the prognosis of patients with ovarian cancer." (PMID 32375633, 2020). "In summary, we identified a novel SP1-12LOX axis that linked DDP-resistance and metastasis in ovarian cancer cells." (PMID 32375633, 2020). "To investigate the potential targets of ZFAS1, we used DIANA TOOLS and found the miR-150-5p was directly regulated by ZFAS1, which further promoted ovarian cancer progression by regulating Sp1." (PMID 28099946, 2017). "Taken together, our findings revealed a critical role of ZFAS1/miR-150-5p/Sp1 axis in promoting proliferation rate, migration activity, and development of chemoresistance in epithelial ovarian cancer." (PMID 28099946, 2017). "ZFAS1 promoted the increased expression of SP1 in ovarian cancer by competitive antagonism against miR-150 to enhance the ability of cell proliferation and chemotherapy resistance for ovarian cancer cells." (PMID 28938617, 2017). "The present study using an antibody that recognizes “SP1” epitope also detected both nuclear and cytoplasmic staining in ovarian cancer clinical samples." (PMID 28859612, 2017). "We have demonstrated that both PI-3 kinase and Src play a role in FAK-induced upregulation of KLF8 in fibroblasts and ovarian cancer cells and in the latter activation of SP1 downstream of Akt plays a likely role." (PMID 26993780, 2016). "Sp1 has been suggested to be responsible for many features of ovarian cancer cells like oncogenic transformation and epithelial to mesenchymal transition for example through activation of KLF8." (PMID 25265318, 2014). "It is overexpressed in breast, thyroid, hepatocellular, prostate, pancreatic, gastric, lung and ovarian cancers, and small molecule inhibitors of Sp1 have been tested in pre-clinical models with successful reduction in tumor burden." (PMID 24626475, 2014). "Expression of Sp1 is frequently increased in human epithelial ovarian cancers and inhibitors of Sp1-dependent transcription both in vitro and in tumor xenografts have been suggested as interesting candidates for treatment." (PMID 25265318, 2014). "For example, KLF8 has been reported to transduce FAK to PI3K to AKT to SP1 signaling to up regulate cyclin D1 expression and enhance the cell cycle progression in ovarian cancer cell." (PMID 23722127, 2013). "More recently, overexpression of claudin-4 in ovarian cancer was found to be partly regulated by a small region in the claudin-4 promoter-containing Sp1 sites." (PMID 18648369, 2008). "Furthermore, ubiquitination assays demonstrated that USP7 knockdown significantly increased c-Myc ubiquitination in Sp1-overexpressing ovarian cancer cells." (PMID 41584043, 2026). "Additionally, we discovered SP1 which was shown to promote chemoresistance and metastasis in ovarian cancer and breast cancer." (PMID 38472332, 2024). "Furthermore, exosomes derived from ETS1-overexpressing ovarian cancer cells mediated pro-tumorigenic effects of omental macrophages via the integrin αvβ5/AKT/Sp1 signaling pathway, consequently promoting omental metastasis of ovarian cancer." (PMID 36477408, 2022).
ovarian carcinoma (continued). "It was reported that ZFAS1 could regulate the expression of Sp1 in ovarian cancer cell malignancy by targeting miR-150-5p." (PMID 35112985, 2022). "In addition, sphingolipid metabolites promote tumor progression by promoting cell proliferation and stimulating chemotactic migration and invasion, such as SP1 in ovarian cancer." (PMID 36568076, 2022). "The role of SP1 in ovarian cancer has been discovered by people." (PMID 34794429, 2021). "In this study we examined the hypothesis that, similar to placenta, CGB expression by ovarian cancers is associated with methylation alterations of the CGB gene cluster, along with changes in the level of the three key transcription factors: AP2, SP1 and SP3." (PMID 31362717, 2019). "Importantly, they also reported that HBXIP was able to stimulate the activity of the Skp2 promoter via transcription factor Sp1 thus promoting the migration of ovarian cancer cells." (PMID 28388957, 2017). "Importantly, the inverse correlation between miR-141 and KLF12 expression was clinically confirmed of that the miR-141/KLF12/Sp1/survivin is a new signaling axis required for anoikis resistance of ovarian cancers during metastatic progression." (PMID 28095864, 2017). "Targeting over-expressed genes in ovarian cancer, including those of transcription factors such as Sp1 might be an appealing strategy to abrogate genes associated with resistance to other drugs." (PMID 25110883, 2014). "SNP285C reduces the binding strength between the Sp1 transcription factor and the MDM2 promoter, and is associated with a significantly reduced risk of spontaneous breast, endometrial and ovarian cancer as well as a reduced risk of ovarian cancer among BRCA1 mutation carriers." (PMID 25327560, 2014). "Beyond SP1-induced MCF2L-AS1, which activates the IGF2/MEK/ERK pathway, SP1 also transcribes multidrug resistance-associated proteins (MRPs) and key enzymes involved in arachidonic acid (AA) metabolism (e.g., 12-lipoxygenase), thereby promoting chemoresistance and metastasis in ovarian cancer." (PMID 40191206, 2025). "Next, to further investigate the regulatory relationship among Sp1, USP7 and c-Myc, we co-transfected ovarian cancer cells with a Sp1-overexpression plasmid and siRNA targeting USP7." (PMID 41584043, 2026). "Specificity protein 1 (SP1) is thought to regulate VEGF expression in several carcinomas, such as pancreatic adenocarcinoma and ovarian cancer." (PMID 38639888, 2024). "MIT exhibits potent antitumor activity by inhibiting Sp1 through distinct mechanisms in PAAD, ovarian cancer, and advanced testicular carcinoma." (PMID 37553567, 2023). "In one of the most detailed studies involving ovarian cancer and MTM analogs, MTM-SDK and MTM-SK, demonstrated considerable inhibition of Sp1 dependent transcription in vitro." (PMID 33445667, 2021). "Our results reveal that SP1-12LOX axis signaling plays a key role in DDP-resistance and metastasis, which provide a new therapeutic target for ovarian cancer." (PMID 32375633, 2020). "Sp1 was the first constitutive eukaryotic transactivator of both housekeeping and TATA genes and it has been observed to be high in epithelial ovarian cancer." (PMID 32050495, 2020). "Taken together, our study revealed that the overexpression of miR-141 augments anoikis resistance in ovarian cancer cells by targeting and repressing the expression of KLF12, which, in turn, competes for binding sites in the survivin promoter with Sp1." (PMID 28095864, 2017). "Several studies have demonstrated that SP1/S1PR1 modulated cell growth, adhesion, migration, and invasion in ovarian cancer cells." (PMID 28831167, 2017).